ZNF354A (zinc finger protein 354A)
Synonyms: EZNF; HKL1; TCF17; KID-1; KID1; HEL104
Tractability: PROTAC: UniProt records ubiquitination sites on it; ubiquitination databases record sites on it.
Gene: Protein-coding gene on chromosome 5 (178,711,512 to 178,732,381, reverse strand). Ensembl gene ENSG00000169131.
Subcellular location: Nucleus
Subcellular location (Human Protein Atlas): Nucleoli; Nucleoplasm; Cytosol
Pathways (Reactome):
Gene expression (Transcription): Generic Transcription Pathway; Regulation of endogenous retroelements by KRAB-ZFP proteins
Gene Ontology:
Molecular function: DNA-binding transcription factor activity, RNA polymerase II-specific; RNA polymerase II cis-regulatory region sequence-specific DNA binding
Biological process: regulation of transcription by RNA polymerase II; sensory perception of sound; regulation of DNA-templated transcription
Cellular component: nucleolus; nucleoplasm; nucleus
Genetic constraint (gnomAD): Loss-of-function variants: 27 observed, 55.52 expected, observed/expected ratio (o/e) 0.49, 90% interval 0.36 to 0.67. The upper end of that interval is the gene's LOEUF score, 0.67, which puts it in group 2 of 6, group 1 being the genes least tolerant of losing a copy. Missense variants: 584 observed, 728.88 expected, observed/expected ratio (o/e) 0.8, 90% interval 0.75 to 0.86. Synonymous variants: 228 observed, 251.55 expected, observed/expected ratio (o/e) 0.91, 90% interval 0.81 to 1.01.
Homologues: Orthologues: macaque ZNF354A (97% identical), dog ZNF354A (91% identical), pig ZNF354A (90% identical), rabbit ZNF354A (87% identical), chimpanzee ZNF354A (85% identical), mouse Zfp354a (83% identical), rat Zfp354a (81% identical), guinea pig ZNF354A (79% identical). Paralogues in human: ZNF354B (86% identical), ZNF658 (45% identical), ZNF879 (45% identical), ZNF726 (45% identical), ZNF7 (44% identical), ZNF708 (44% identical), ZNF717 (44% identical), ZNF33B (44% identical), ZNF254 (44% identical), ZNF484 (44% identical), ZNF724 (44% identical), ZNF311 (43% identical), and 164 more.
Diseases named in the same sentence as ZNF354A in open-access papers:
ZNF354A is named in the same sentence as 2 diseases in open-access papers, as found by Europe PMC text mining. Sharing a sentence is not in itself a finding about the gene and the disease. The quoted sentences say what the papers report.
cancer (2 papers, 2021 to 2023). A tumor composed of atypical neoplastic, often pleomorphic cells that invade other tissues. "The literature shows that some KZNFs are up-regulated in cancer, including ZNF695, ZNF320, ZNF200, ZNF354A, ZNF707, ZNF138 and so on." (PMID 37370088, 2023).
ZNF354A also shares sentences with these, for which no sentence is quoted: tumor (1 paper).